CDK2AP1 (cyclin dependent kinase 2 associated protein 1)
Diseases named in the same sentence as CDK2AP1 in open-access papers (continued):
Sharing a sentence is not in itself a finding about the gene and the disease.
tumor (continued). "Furthermore, pathways directly related to the immune response against tumor cells such as leukocyte activation involved in inflammatory response, regulation of leukocyte activation, interleukin-6 production were under-represented in CDK2AP1 gene set enrichment analysis." (PMID 36362115, 2022). "Various evidences suggest that CDK2AP1 modulates the actions of transforming growth factor-B1 (TGFB1) and retinoblastoma (Rb) protein to suppress tumor growth." (PMID 36105112, 2022). "Using this cut-off, tumor immune-infiltration strongly correlated with patients showing more than 35% of tumor cells negative for CDK2AP1 (Chi-square test = 0.004)." (PMID 40112045, 2025). "When considering the CDK2AP1 staining intensity status, the relative proportion of stromal and tumor cells did not significantly change between CDK2AP1-low/negative and positive cores." (PMID 40112045, 2025). "Using this cut-off, disease-free survival negatively correlated with patients showing more than 45% of tumor cells negative for CDK2AP1 (Log rank P = 0.02)." (PMID 37217493, 2023). "Immunohistochemical results obtained from the Human Protein Atlas (HPA) database showed that CDK2AP1 was expressed at a higher level in HCC tumor tissues than in non-tumor tissues." (PMID 36105112, 2022). "In the future, we can try to measure the expression of CDK2AP1 in HCC surgical specimens to reflect the degree of malignancy of HCC patients, and even evaluate the local immune status of tumor tissues, so as to predict the efficacy of immunotherapy and the prognosis of patients." (PMID 36105112, 2022). "Regardless of CDK2AP1 status, CD68+ macrophages were mainly distributed in the periphery (P = .02), whereas CD3+ lymphocytes were primarily found infiltrating the tumor core (P = .009), as were monocytes (CD14+; P = .015)." (PMID 40112045, 2025).
cancer (12 papers, 2015 to 2025). A tumor composed of atypical neoplastic, often pleomorphic cells that invade other tissues. "Given the significant association of CDK2AP1 expression with tumorigenesis, CDK2AP1 may play a role in oncogenesis and serves as a molecular target for cancer therapy." (PMID 26515287, 2015). "The anti-correlation between CDK2AP1 expression in the nuclei and that of miR-21-5p in the cytoplasm is clearly visible in the higher magnification inlets of the cancer fields, and the digital representation of the expression densities." (PMID 37217493, 2023). "High degree of expression heterogeneity was observed even with miR-21, i.e., the most frequently overexpressed miR among human cancers, thus suggesting that the regulation of CDK2AP1 expression involves multiple noncoding RNAs." (PMID 37217493, 2023). "Pan-Cancer data analysis for CDK2AP1 mRNA expression in 22 tumors revealed CDK2AP1 was significantly upregulated in all 22 tumors including PCa." (PMID 36362115, 2022). "BioGPS database was used to show the expression levels of CDK2AP1 in 10 cancer cell lines and 10 normal cell lines." (PMID 36105112, 2022). "Recently, decreased CDK2AP1 expression was shown to correlate with tumor metastasis and survival in patients with cancer." (PMID 26515287, 2015). "The function of CDK2AP1 as initially assessed in multiple cancer cell lines indicates its role in regulation of apoptosis, proliferation and invasion." (PMID 25785833, 2015). "Cyclin-dependent kinase 2-associated protein 1 (CDK2AP1), also named as DOC-1 (deleted in oral cancer-1), is a growth suppressor originally isolated from normal hamster oral keratinocytes." (PMID 26515287, 2015). "However, the role of CDK2AP1 is still ambiguous, as it has a complex role in different types of cancer." (PMID 37958905, 2023). "Downregulation of CDK2AP1 in cancer cells could thus result in beneficial growth inhibitory effects." (PMID 25785833, 2015). "Therefore, further studies are needed to identify the pathway responsible for the observed anti-tumorigenic effects of CDK2AP1 knockdown, so its potential can be examined in the appropriate cancer cell lines." (PMID 25785833, 2015). "All of these findings support the notion that CDK2AP1 may be important in cancer immunotherapy." (PMID 36105112, 2022). "We then established two categories of CDK2AP1 immunoreactivity based on the staining intensity and an optimal threshold of 45% of cancer cells negative for CDK2AP1." (PMID 37217493, 2023). "Therefore, we established 2 categories of CDK2AP1 immunoreactivity based on the staining intensity, and an optimal threshold of 35% cancer cells negative for CDK2AP1 was found (P = .024)." (PMID 40112045, 2025).
carcinomas of the (1 paper, 2023). "Last, we show that CDK2AP1 loss, as the result of miRNA expression, correlates with overall survival, thus highlighting the clinical relevance of these processes for carcinomas of the oral cavity." (PMID 37217493, 2023).
CDK2AP1 also shares sentences with these, for which no sentence is quoted: Esophageal carcinoma (2 papers); colon adenocarcinoma (1); colorectal cancer (1); esophageal squamous cell carcinoma (1); fibrosarcoma (1); Glioblastoma multiforme (1); head and neck squamous cell carcinoma (1); melanoma (1); metastatic prostate carcinoma (1); non-small cell lung carcinoma (1); ovarian carcinoma (1); Pan (1); tongue squamous cell carcinoma (1).